IL10 (interleukin 10)
Diseases named in the same sentence as IL10 in open-access papers (continued):
Sharing a sentence is not in itself a finding about the gene and the disease.
Stroke (continued). "However, in contrast to the trend towards increased IL-10 expression with clenbuterol treatment at 4 h post-stroke, IL-10 mRNA expression was actually reduced by 4.78-fold in peri-infarct cortex of clenbuterol-treated mice relative to saline-treated mice at the 3-day sub-acute time point." (PMID 31138227, 2019). "Additionally, previous findings suggest that Interleukin 10 (IL-10) may reduce the capability of 5-TH synthesis in the brain, which is observed in patients after a stroke." (PMID 31817010, 2019). "Additionally, previous findings suggest that Interleukin 10 (IL-10) may reduce the capability of 5-TH synthesis in the brain, which is observed in the patients after a stroke." (PMID 31817010, 2019). "It is well known that microglial cells are able of producing anti-inflammatory cytokines such as IL-10 and transforming growth factor-β1 (TGFβ1), which have neuroprotective effects as it was observed in experimental animal models of traumatic injury and stroke." (PMID 30518432, 2018). "Furthermore, an excessive IL-10 response may even worsen stroke recovery, depending on genetics and sex." (PMID 28373915, 2017). "In addition, we also examined whether stroke severity is a key determinant of IL-10 level in patients." (PMID 28154551, 2017). "However, only IL-6 and IL-10 were positively correlated with NIHSS on day 3 after stroke." (PMID 27682880, 2017). "Interestingly, in our study, IL-10 levels were higher in females who developed post-stroke UTIs versus those females who did not, and this association was not seen in males." (PMID 26462256, 2015). "This suggests that IL-10 secretion is related to acute cardiogenic thrombus, either to its formation, resolution or to the acute consequences of its embolism, and might have potential to improve the differential diagnostics of stroke/TIA etiology." (PMID 25923658, 2015). "IL-10 may have potential to improve differential diagnostics of stroke with unknown etiology." (PMID 25923658, 2015). "For determination if initial levels (at 6 h) of IL-10, IL-6 and CRP are independently associated with infection in ischemic stroke patients, we performed a binary logistic regression analysis that was adjusted for NIHSS on admission, stroke etiology, and peak levels of S100B." (PMID 25613713, 2015). "In addition, IL-10 has been documented to directly protect neurons from stroke-induced damage." (PMID 26366999, 2015). "In addition, epidemiological data indicate that individuals with elevated IL-10 plasma levels have a reduced risk of stroke, and that subjects with a history of stroke have lower levels of IL-10 than those without previous stroke." (PMID 25923658, 2015). "However, nasal MOG tolerization in stroke induced more IL-10 and less CD11b cells than oral MOG." (PMID 25309322, 2014). "In addition, we examined the change in IL-10 levels after stroke in hypertensive rats." (PMID 24499655, 2013). "In our study, the salivary concentration of IL-2, IL-5, IL-7, IL-10, IL-12 (p70), IL-13, IL-15, and IFN-α2 was below the detection level in healthy controls (most commonly) and in stroke patients." (PMID 40520895, 2025). "Key inflammatory cytokines in stroke include interleukin-1 (IL-1), TNF-α, interleukin-6 (IL-6), interleukin-10 (IL-10), and transforming growth factor-β (TGF-β)." (PMID 40362194, 2025). "The emerging immunosuppressive landscape in the subacute and chronic phases of stroke—marked by an expansion of Tregs, MDSCs, and increased TGF-β and IL-10 production—mirrors the immune evasion mechanisms seen in metastatic progression." (PMID 40909970, 2025). "In terms of inflammatory response, treadmill training significantly decreased the concentrations of IL-6 and IL-17 and increased the levels of IL-10 and TGF-β, suggesting that exercise has a modulating effect on post-stroke inflammation." (PMID 40837062, 2025).
Stroke (continued). "In an experimental stroke model, the administration of BDNF through the nasal route was found to increase anti-inflammatory cytokine IL-10 levels but to decrease pro-inflammatory cytokine tumour necrosis factor-alpha levels." (PMID 38707431, 2024). "Inflammatory response was determined by detecting levels of cytokines (interleukin-2 [IL-2], IL-4, IL-5, IL-8, IL-6, IL-10, IL-12p70, IL-17, tumor necrosis factor-α [TNF-α], interferon-γ [IFN-γ], IFN-α, and IL-1β) within 14 days after stroke onset." (PMID 38902691, 2024). "As important immunological mediators in post-stroke responses, cytokines have been confirmed as independent predictors of SAP, including IL-6, IL-10, and TNFα." (PMID 37065465, 2023). "Production of other pro-inflammatory cytokines (TNF-alpha, IL-6) is significantly increased at 24 h of stroke which also initiates the synthesis of anti-inflammatory cytokines to protect the tissue itself (TGF-beta, IL-10)." (PMID 37822799, 2023). "Specific inflammatory blood markers correlate with outcomes after stroke, including proinflammatory cytokines like IL-1, IL-6, TNF, as well as anti-inflammatory cytokines like TGF and IL-10." (PMID 36691064, 2023). "In this study were analysed glutamate, IL-1β, IL-6, IL-10 and TNF-α according to the time of stroke." (PMID 36835156, 2023). "The reduced neuroprotective effects of Il10-KO and Tgfa-KO CD8+ TRLs nonetheless support the essential role of these 2 molecules in the beneficial effects of CD8+ TRLs in stroke brains." (PMID 35912857, 2022). "In particular, we found that IL-10 and ETGF collaborated to exert neuroprotective effects after stroke." (PMID 35912857, 2022). "The M2 phenotype has anti-inflammatory effects and secretes anti-inflammatory cytokines such as IL-10, IL-4, and transforming growth factor beta (TGF-β), which further protect neurological function and improve prognosis after stroke." (PMID 36685518, 2022). "Following stroke, substantial skewing of the cytokine response is observed, with a shift from a TH1 (IFNγ) to TH2 (IL-4, IL-10) phenotype." (PMID 38566903, 2022). "In monocytes isolated from stroke patients, we found significantly higher release of IFN-γ and IL-10 as compared to that from monocytes isolated from healthy controls (p < 0.05)." (PMID 36277912, 2022). "The current study, therefore, investigated the associations between SNPs of inflammatory molecules, consisting of IL-1β, TNF-α, IL-6, IL-10, IL-18, interferon-γ (IFN-γ) and C-reactive protein (CRP), and PSD at 2 weeks after stroke (early-onset PSD)." (PMID 36225923, 2022). "Key cytokines related to inflammation in stroke are tumor necrosis factor-α (TNF-α), interleukin (IL)-1, IL-6 and IL-10." (PMID 35631536, 2022). "The pro-inflammatory (TNF-α, IL-1β, IL-6, IL-12 p40, and MIP-1α), and the anti-inflammatory (IL-4 and IL-10) mediators were examined by ELISA in IRF5 or IRF4 CKO aged mice plasma, 3 days after stroke." (PMID 35963621, 2022). "There was a negative correlation between the National Institutes of Health Stroke Scale (NIHSS) score and IL-10 serum levels (r (Spearman) = −0.221, P = 0.001)." (PMID 34336007, 2021). "In particular, microglia exhibited a dominant neuroprotective M2-like response (phagocytosis and tissue repair) for the first seven days post stroke, characterized by increased expression levels of CCL22, IL10, CD206, arginase-1 and TFG-β." (PMID 34194419, 2021). "To visualize the spatial distribution and cellular source of IL-10 in post-stroke brains, we performed immunohistochemistry using a reporter mouse expressing a green fluorescent protein (GFP) under the control of the IL-10 promotor." (PMID 34772416, 2021). "We have demonstrated that assessment of TNF-α, IL-6, and IL-10 levels in both NWS and SWS significantly differentiates stroke patients from healthy controls." (PMID 34433866, 2021).
Stroke (continued). "Nevertheless, both the concentration (pg/mL), salivary output (pg/min), and specific content (per mg protein) of TNF-α and IL-6 were significantly higher, whereas IL-10 was statistically lower in NWS and SWS of stroke patients compared to controls." (PMID 34433866, 2021). "In our patients, the content of pro-inflammatory TNF-α and IL-6 was higher, and anti-inflammatory IL-10 was lower in both NWS and SWS of stroke patients." (PMID 34433866, 2021). "Although candidate mediators (i.e., serum TMAO, IL-17, IL-10, and BDNF) were comparable in the acute phase of stroke, there were differences in biological functions such as the membrane transport and amino acid metabolism between the two groups." (PMID 35153980, 2021). "Cytokines are important immune mediators in the post-stroke response, so they have been studied as predictors of SAI, including pro-inflammatory IL-6 and anti-inflammatory IL-10." (PMID 34092245, 2021). "TNF-α/IL-10 and IL-6/IL-10 ratio were also significantly higher in NWS and SWS of stroke patients, indicating an intensification of the inflammatory process and a limited anti-inflammatory role of IL-10." (PMID 34433866, 2021). "Proinflammation cytokines, such as IL-6, IL-10, and TNF-α, have been shown to be elevated in the rat models of stroke that were subjected to a pretreatment of RIC." (PMID 34439830, 2021). "Anti-inflammatory cytokines from regulatory T cells such as IL-10 and TGF-β interact with both positive and negative regulators of neural regeneration and influence the repair process after a stroke." (PMID 33042113, 2020). "Additionally, sex differences may exist in the role of IL-10 in stroke recovery." (PMID 30700305, 2019). "Here, we also found that levels of IL-1β, IL-1RA, IL-10, IL-13, IL-15, Flt-3L, Fractalkine, EGF, G-CSF and GM-CSF were lower in the severe stroke group." (PMID 31164999, 2019). "During post-stroke NVU recovery, microglia transform to a M2 pro-remodeling phenotype, releasing anti-inflammatory cytokines (e.g., IL10) and growth factors." (PMID 31543756, 2019). "They regulate expression of molecules important in stroke recovery including IL4, IL10, and BDNF in microglia and down-regulate iNOS and IL6." (PMID 31543756, 2019). "Lactadherin treatment significantly increases anti-inflammatory factor (IL10) expression in ischemic brain and decreases IL1β expression in plasma compared to PBS and BDMP treated stroke mice, respectively." (PMID 31993045, 2019). "Adjusted logistic regression analysis revealed that infection was independently associated with splenic volume, leukocyte counts, the percentage of Treg cells, and the serum levels of CRP, IL-10, and IFN-γ on day 3 after stroke (all p < 0.05)." (PMID 27682880, 2017). "Several studies have shown that the percentages of cytotoxic T cells, natural killer (NK) cells, and B lymphocytes, and serum levels of TNF-α, IFN-γ, C-reactive protein (CRP), IL-4, IL-6, IL-10, and TGF-β are altered after stroke." (PMID 27682880, 2017). "Following stroke huge panoply of proinflammatory cytokines that are released in the bloodstream and detectable in the serum, besides IL-6 and TNF-α, also IL-10, IL-4, IL-17, IL-23, and TGF-β increase." (PMID 28373915, 2017). "Like IL-10, overexpression or administration of TGF-β1 reduced ischemic lesion size and improved neurological outcomes in experimental stroke model." (PMID 28936196, 2017). "Here, we comprehensively review the current knowledge regarding the role of IL-10 in modulating outcomes following acute brain injury, including traumatic brain injury (TBI) and the various stroke subtypes." (PMID 28659854, 2017). "This protection is specifically mediated by IL-10 secreted from CD4+ T cells, which were able to protect mice from stroke only when originating from WT mice." (PMID 28659854, 2017).
Stroke (continued). "In BALB/c mice at 7 weeks post-stroke, levels of G-CSF, IL-2, IL-6, IL-17, IP-10, MCP-1, and RANTES were increased, and levels of GM-CSF, IFNγ, IL-10 were decreased compared to sham mice." (PMID 27600707, 2016). "Treatment with NBE-MSC-MVs greatly upregulated expression of the anti-inflammatory cytokines IL-10 (1.9-fold increase) and TSG-6 (3.2-fold increase) in the rat stroke model." (PMID 27609711, 2016). "Subsequently, we analyzed the correlation between the mRNA expression of Foxp3, IL-10, TNF-α and iNOS with the death and stroke risks." (PMID 27115869, 2016). "In BALB/c mice at 1 week post-stroke G-CSF, IP-10, KC, MCP-1, MIP-1α, and MIP-1β were increased, and levels of IL-1β, IL-10, and IL-13 were decreased compared to sham mice." (PMID 27600707, 2016). "Previous studies showed it has a strong inhibitory effect of IL1β, IL6, IL10, TNF and other circulating cytokines, and suggested a potential therapeutic for stroke patients." (PMID 27672514, 2016). "In the current study, a significantly increased baseline serum levels of IL-10 and TNF-α were found in stroke patients (both SAI & nSAI groups), compared to control individuals (P = 0.01 & 0.002, respectively)." (PMID 27453748, 2016). "Production of IL-1, IL-6, IL-10 and TNF-α as a consequence of cerebral insult from stroke can be sensed by the hypothalamus to activate the HPA axis for excessive glucocorticoid release." (PMID 26742037, 2016). "In the adult rodent, M1 markers (iNOS, CD11b, CD16, and CD32) were still elevated at 14 days after stroke, while M2 markers (CD206, Arg-1, Ym1/2 and IL-10) were decreased at 7 days after ischemia." (PMID 27126393, 2016). "Brain cytokine analysis at 24 h indicated that stroke resulted in substantially higher mean levels of IL-4, IL-6, TNF-α, IFN-γ, IL-10, and IL-17A in both C57Bl/6 and FVB mice." (PMID 25477780, 2014). "CD4+ regulatory T cells are upregulated following stroke and CD8+ regulatory T cells are known to suppress CD4+ and CD8+ T cell proliferation and IFNγ production by secreting IL-10." (PMID 25309326, 2014). "This study presents a mechanistically grounded computational model that captures the nonlinear interplay between TNF-α, IL-6, and IL-10 during acute post-stroke inflammation." (PMID 41557608, 2026). "Simulations of the post-stroke cytokine network over a 72-hour period yielded temporally distinct trajectories for tumor necrosis factor-alpha (TNF-α), interleukin-6 (IL-6), and interleukin-10 (IL-10), reflecting the transition from pro-inflammatory activation to immune resolution." (PMID 41557608, 2026). "Furthermore, while interleukin-1 (IL-1) is a critical mediator in post-stroke inflammation, our model focuses on the TNF-α/IL-6/IL-10 axis to establish a foundational understanding of their core feedback loops." (PMID 41557608, 2026). "Immunological and inflammatory biomarkers, including IL-1β, IL-6, TNF-α, IL-10, IL-8, IL-17, and CRP, have become indispensable tools in stroke research, offering insight into how the immune system shapes both the extent of brain injury and the trajectory of recovery." (PMID 40869247, 2025). "Meanwhile, levels of anti-inflammatory cytokines such as IL-10 and TGF-β rise in the resolution phase and are linked not only to tissue repair but also to stroke-induced immunosuppression and increased infection risk." (PMID 40869247, 2025). "An increasing body of research has reported a correlation between cognitive impairment following stroke and alterations in the production of biomarkers, including C-reactive protein (CRP), interleukin 6 (IL-6) and interleukin 10 (IL-10), which are found in blood, urine and other body fluids." (PMID 38984252, 2024). "Stroke-induced alterations in microglia and astrocytes emerge as critical in PSD evolution, modulating neurotransmitter dynamics, neuronal viability, and cytokine release, including pro-inflammatory IL-1β, IL-6, TNF-α, and anti-inflammatory IL-10." (PMID 38377025, 2024).
Stroke (continued). "In stroke, B-cell transfer in normal mice reduced cerebral infarct volume compared to B-cells lacking IL-10." (PMID 38550918, 2024). "After stroke onset, activation of microglial AHR by microbial Trp-derived ligands was corroborated to suppress the expression of proinflammatory and neurotoxic genes, including TNF, IL6, IL12A, and NOS2, and boost anti-inflammatory IL10 expression." (PMID 39195495, 2024). "Higher levels of IL-10 and tumor necrosis factor (TNF) were found in patients with AF, compared with controls, and the latter was also suggested as a predictive marker of stroke in patients with NVAF." (PMID 36834735, 2023). "Importantly, taking myelin oligodendrocyte glycoprotein (MOG) through the nose triggers Il-10 secretion from CD4+ T cells, which helps reduce stroke-related disability." (PMID 36793730, 2023). "In order to further explore the implication of TREG-microglia interactions to modulate the post-stroke inflammatory environment, we tested the therapeutic potential of the known anti-inflammatory properties of TREG via IL10 on the local microglial immune milieu." (PMID 36512388, 2022). "In addition, microglia M2-induced chitinase-3-like protein 3 (Ym1/2), IL-10, and TGF-β secretion promoted angiogenesis, thereby decreasing BBB secretion and improving stroke outcomes." (PMID 35055089, 2022). "In a transient MCAO model, the use of minocycline promoted microglia M2 polarization significantly reduced TNF and IL-1β levels and increased TGF-β, IL-10 and chitinase-like proteins (YM1) levels, thereby reducing cerebral infarct size, promoting vascular remodeling, and improving stroke prognosis." (PMID 35356292, 2022). "We did not observe any difference in IL-10 expression between ischemic and non-ischemic sides in female rat brain during recovery phase of stroke." (PMID 35413803, 2022). "Moreover, Il10-KO CD8+ TRL–treated mice exhibited increased brain expression of IL-6, CCL1, and CCL2 after stroke compared with WT CD8+ TRL–treated mice." (PMID 35912857, 2022). "The anti-inflammatory cytokine IL-10 released by T regulatory cells largely prevents the Ang II evoked release of •O2 and restores NVC,197 which is consistent with the cerebroprotective function of IL-10 after stroke in mice." (PMID 35581998, 2022). "The one‐way ANOVA analysis revealed that IL‐1β and IL‐6 transcripts were upregulated in response to stroke (p < 0.001), while mRNA expression of IL‐10 did not change relative to sham (p = 0.20)." (PMID 35715988, 2022). "M2 phenotype is anti-inflammatory, which secretes anti-inflammatory cytokines such as interleukin-4 (IL-4), interleukin-10 (IL-10), transforming growth factor-β (TGF-β) and some neurotrophic factors, which facilitate brain function recovery and improve the prognosis of stroke." (PMID 35356292, 2022). "In addition, plasma TNF-α and IGF-1 levels were increased and decreased in stroke patients, respectively, and miR-424 levels in both lymphocytes and neutrophils were negatively correlated with plasma TNF-α, IL-10, or IGF-1 levels." (PMID 36275741, 2022). "Moreover, inflammatory markers [e.g., Interleukin (IL)-10] and growth factors like transforming growth factor (TGF) -β contribute as other repair-related molecular changes after stroke." (PMID 35413803, 2022). "With this in mind, a targeted antagonization of IL-17A seems promising, irrespective of individual IL-10 levels pre-stroke." (PMID 34772416, 2021). "Thus, the role of genetic polymorphism of IL-10 in stroke prognosis could not be confirmed." (PMID 34336007, 2021). "Since NS19504 treatment promoted the outcome of stroke, we detected whether inflammation affects the significant difference between groups, and the mRNA levels of inflammation factors TNF-α, IL-1β, IL-6, IL-10, and TGF-β were examined." (PMID 34276309, 2021).